KRTAP3-1 (keratin associated protein 3-1)
Description:
In the hair cortex, hair keratin intermediate filaments are embedded in an interfilamentous matrix, consisting of hair keratin-associated proteins (KRTAP), which are essential for the formation of a rigid and resistant hair shaft through their extensive disulfide bond cross-linking with abundant cysteine residues of hair keratins. The matrix proteins include the high-sulfur and high-glycine-tyrosine keratins.
Synonyms: KAP3.1; KRTAP3.1
Tractability: No criterion of Open Targets' tractability assessment is met for any kind of drug.
Gene: Protein-coding gene on chromosome 17 (41,008,521 to 41,019,324, reverse strand). Ensembl gene ENSG00000212901.
Pathways (Reactome):
Developmental Biology: Keratinization
Gene Ontology:
Molecular function: protein binding; structural molecule activity
Cellular component: cytosol; keratin filament
Genetic constraint (gnomAD): Loss-of-function variants: 5 observed, 5.97 expected, observed/expected ratio (o/e) 0.84, 90% interval 0.44 to 1.66. That is too few expected variants to judge how well the gene tolerates losing a copy. Missense variants: 130 observed, 134.09 expected, observed/expected ratio (o/e) 0.97, 90% interval 0.84 to 1.12. Synonymous variants: 47 observed, 52.14 expected, observed/expected ratio (o/e) 0.9, 90% interval 0.71 to 1.15.
Homologues: Orthologues: chimpanzee KRTAP3-1 (98% identical), mouse Krtap3-1 (87% identical), rat Krtap3-1 (86% identical), rabbit KRTAP3-1 (82% identical), guinea pig KRTAP3-1 (78% identical), dog KRTAP3-1 (64% identical), pig KRTAP3-1 (63% identical). Paralogues in human: KRTAP3-2 (74% identical), KRTAP3-3 (72% identical), KRTAP24-1 (36% identical).
Diseases named in the same sentence as KRTAP3-1 in open-access papers:
KRTAP3-1 is named in the same sentence as 1 disease in open-access papers, as found by Europe PMC text mining. Sharing a sentence is not in itself a finding about the gene and the disease.
KRTAP3-1 shares sentences with these, for which no sentence is quoted: tumor (1 paper).